BRAF (B-Raf proto-oncogene, serine/threonine kinase)
Diseases named in the same sentence as BRAF in open-access papers (continued):
Sharing a sentence is not in itself a finding about the gene and the disease.
melanoma (continued). "The amplification in cyclin D1, which can be observed in 15–20% of BRAF-mutant melanomas, is associated with a higher rate of resistance to BRAF inhibitors." (PMID 26171394, 2015). "BRAF mutations are frequently detectable in melanoma (50-60% of cases), papillary thyroid cancer (40-60%), colorectal cancer (about 5-10%), pilocytic astrocytoma (10-15%) and non-small-cell lung cancer (NSCLC; 3-5%)." (PMID 26431495, 2015). "Recent discoveries in cell signaling pathways that control cellular proliferation have provided a greater understanding of the biology that underlies melanoma and have elucidated the central role of BRAF kinase." (PMID 25789737, 2015). "Due to the aggressiveness of melanoma and its unique ability to develop resistant mutations even after treatment with combination of BRAF and MEK inhibitors, it will become necessary to develop alternative forms of therapy to evade resistance." (PMID 26139106, 2015). "Vemurafenib is an oral BRAF inhibitor selective for the V600E mutation, and has been proven to be effective in treating advanced melanoma patients with the same mutation." (PMID 25706985, 2015). "Vemurafenib, an oral anti-BRAF V600 kinase inhibitor, is indicated for the treatment of advanced malignant melanoma for patients whose tumors harbor the BRAF V600 mutation." (PMID 26152183, 2015). "It has been reported that melanoma cells, owing to the BRAF mutation, depend majorly on glycolysis for ATP generation, and exhibit dysfunctional oxidative phosphorylation." (PMID 26484566, 2015). "When fisetin was combined with sorafenib, co-targeting of these two parallel signaling pathways resulted in enhanced apoptosis in BRAF-mutated melanoma cells." (PMID 26299806, 2015). "Recently, some groups have reported that the combination of RAF inhibitors and MEK inhibitors shows significant synergistic anti-tumor effects in melanoma with v-raf murine sarcoma viral oncogene homolog B1 (BRAF) V600E mutation." (PMID 26630652, 2015). "Although BRAF mutations are uncommon, they represent an important therapeutic target due to the availability of individualized therapies in clinical use for melanoma and the promising results reported in ongoing clinical trials for NSCLC patients." (PMID 25789627, 2015). "Mutational activation of BRAF gene is already known to occur in melanoma, glioblastoma, thyroid, lung, colon and hematological malignancies." (PMID 26643872, 2015). "Among 127 samples from 77 patients suffering from malignant melanoma, we found 60 samples from 31 patients to be positive for BRAF mutations (n = 28, V600E; n = 3, V600K) by Sanger sequencing." (PMID 25318602, 2015). "Vemurafenib is a target drug that is effective for melanoma tumors with V600E gain-of-function mutation in BRAF gene." (PMID 26320181, 2015). "Five recently published studies have analyzed the BRAF mutation status of melanoma samples with different molecular methods." (PMID 26498143, 2015). "For example, the BRAF inhibitor vemurafenib is approved for the treatment of patients whose melanoma harbors the V600E mutation, which is thought to be a driver mutation." (PMID 25625193, 2015). "A total of 245 tumor specimens (212 primary melanomas and 33 melanoma cell lines) was screened for mutations in BRAF, NRAS, and PIK3CA genes by automated direct sequencing." (PMID 25627962, 2015). "For example, approximately 50 % of malignant melanomas harbor a BRAF activating mutation, the majority of these being BRAFV600E, which results in constitutive activation of BRAF and increased activation of the MAPK pathway." (PMID 26104682, 2015). "BRAF mutations that can be found in the majority of PTC are known to activate autophagy in melanoma but possibly also in PTC." (PMID 25741318, 2015). "Vemurafenib is an effective treatment drug for malignant melanoma that is BRAF mutation-positive; however, it is known to have little effect on BRAF mutation-positive colon cancer." (PMID 25936694, 2015).
melanoma (continued). "Inhibition of RAF/MEK/ERK signaling in melanoma cells with BRAF mutations results in cell cycle arrest and promotion of cell death, including apoptosis." (PMID 26236691, 2015). "All of the melanoma cells tested here harbor a V600E point mutation in BRAF, a mutation that occurs in approximately 50% of patients suffering from melanoma." (PMID 26029997, 2015). "Results of the clonogenic assay clearly demonstrated that combination treatment effectively inhibited the colony number and size of BRAF-mutated melanoma cells (A375, SK-MEL-28 and RPMI-7951)." (PMID 26299806, 2015). "In the present investigation, we found that fisetin inhibited expression of PI3K and enhanced expression of PTEN as well as decreased phosphorylation of AKT and mTOR in BRAF-mutated melanoma cells." (PMID 26299806, 2015). "The increased risk to melanoma and nevi from longer telomeres has been attributed to delayed melanocytes senescence, which increases the chance of mutations in the oncogenic BRAF gene." (PMID 25871393, 2015). "BRAF codon 600 mutation testing of melanoma patients is mandatory for the choice of the most appropriate therapy in the clinical setting." (PMID 26690267, 2015). "Recently, novel molecular-targeted therapies have been approved by the FDA for first-line treatment in advanced melanoma i.e., vemurafenib for BRAF V600E mutation (BRAFmt)." (PMID 26085332, 2015). "Between December 2012 and April 2013, 420 melanoma samples were consecutively included in this BRAF V600 mutation parallel testing study conducted in 12 platform laboratories, with a median number of 32 samples (min 20-max 52) in each laboratory." (PMID 25789737, 2015). "The crucial trial for vemurafenib to be approved for treatment was BRIM-3, a phase III study comparing vemurafenib to dacarbazine in unresectable, previously untreated melanoma in stage IIIC or IV with BRAF V600 mutation." (PMID 26171394, 2015). "The discovery that approximately 40%–50% of malignant melanomas contain a mutation in BRAF at codon 600 gave scientists a new approach to tackle this disease." (PMID 26393652, 2015). "Current melanoma research focuses on the contribution of miR dysregulation in malignant melanoma and its relation to BRAF and NRAS oncogenic mutations." (PMID 26116372, 2015). "For patients who have BRAF V600 mutation-positive melanoma, vemurafenib was the most widely used first-line treatment option (especially in those with a high disease burden)." (PMID 26700304, 2015). "Along with the same line of thought, the idea of combining a BRAF inhibitor with a MEK inhibitor has been tested for the treatment of BRAF mutated melanomas." (PMID 25645078, 2015). "Very recently the ErbB3 receptor has been shown to act as a central node promoting survival of BRAF mutated melanoma." (PMID 26208478, 2015). "Currently, Sanger sequencing and real-time PCR are the clinical methods that are used to detect BRAF mutations in diagnostic laboratories, including selecting melanoma patients eligible to Vemurafenib treatment." (PMID 25784606, 2015). "Idylla detected BRAF V600 mutations in 12 of 30 melanomas (40%), 1 of 23 colorectal cancers (4%), and 2 of 5 papillary thyroid cancers (40%) but did not detect BRAF V600 mutations in breast cancers or NSCLC." (PMID 26330075, 2015). "In the present investigation, the non-toxic flavonoid fisetin has shown potential to inhibit melanoma cell growth and induce apoptosis of BRAF-mutated melanoma cells by reducing PI3K signaling." (PMID 26299806, 2015). "BRAF mutations seem to be associated also to anatomical sites of the primary lesion, with melanomas on the trunk presenting higher rate of mutations at BRAF gene, as already shown." (PMID 26834525, 2015). "Phase III trial (BREAK-3) enrolled patients with stage IV or unresectable stage IIIC melanoma harboring BRAF V600E mutation." (PMID 26171394, 2015).
melanoma (continued). "In this paper we first demonstrate that ErbB3/AKT hyperphosphorylation occurs in BRAF mutated melanoma cell lines following exposure to BRAF and/or MEK inhibitors." (PMID 26208478, 2015). "In 10 melanoma patients, BRAF V600E mutation resulted in 100% sensitivity, specificity and accuracy between cfDNA and direct DNA sequencing of tumor FFPE specimens." (PMID 26452027, 2015). "Previous studies revealed that approximately 50% of melanomas have activating BRAF mutations, and abundant data validate BRAFV600E as a therapeutic target in melanoma." (PMID 26033450, 2015). "In order to explore the antitumor activity of prenylation inhibition we investigated the response to zoledronic acid treatment in thirteen human melanoma cell lines with known BRAF, NRAS and PTEN mutational status." (PMID 25646931, 2015). "Another common way of activating the MAPK pathway is through the BRAF V600E mutation, which is detected in wide range of tumors such as melanomas, thyroid cancer, craniopharyngioma and LGG, especially PXA and GG." (PMID 25883769, 2015). "Activating BRAF V600 mutations have been shown to occur in 40%–60% of malignant melanomas, including in recent reports based on analyses of French patients." (PMID 25789737, 2015). "In BRAF-mutated melanomas, metformin used in combination with the BRAF inhibitor vemurafenib has shown a synergic antitumor effect to induce melanoma cell death." (PMID 26322273, 2015). "There was also an indication that low-grade melanomas were more likely to carry BRAF mutations while high-grade tumors were more likely to carry NRAS mutations although this subset analysis was based on a small number of tumors." (PMID 25871393, 2015). "Somatic BRAF mutations, in particular the V600E mutation within the kinase domain, have been frequently found in melanomas, thyroid, colorectal, and lung cancer." (PMID 26513174, 2015). "In patients with BRAF-mutated melanoma and good performance status, a BRAF inhibitor is reserved for unequivocal evidence of disease progression after immunotherapy." (PMID 25815245, 2015). "PTEN-null mutations are present in 20% of melanoma cases furthermore PTEN null mutation is often concurrent with BRAF mutation in melanoma." (PMID 25646931, 2015). "One publication assessed three ongoing trials using vemurafenib for BRAF mutation–positive advanced melanoma to provide management recommendations for dermatologic adverse effects." (PMID 26705496, 2015). "Like sorafenib, oral administration of fisetin monotherapy significantly inhibited the tumor growth of BRAF-mutated melanoma cells in nude mice by inhibiting tumor cell proliferation markers (PCNA, Ki67 and cyclin D1)." (PMID 26299806, 2015). "Over 50% of melanomas bear BRAF mutations at the advanced stage, of which approximately 80% appear as the substitution of glutamic acid (E) for valine (V) in codon 600, known as the V600E mutation, and approximately 16% as the V600K mutation." (PMID 26370727, 2015). "Regarding the BRAF V600E mutation, it has already been implemented as a predictive factor guiding therapy in malignant melanoma and is currently explored as a potential predictive marker in colorectal cancer as well as in other malignancies." (PMID 25318602, 2015). "BRAF mutations occur in 46% to 48% of patients with melanoma and are more likely to be found in younger patients and on intermittently sun-exposed tumors." (PMID 26557410, 2015). "BRAF mutations occur in around 40–60% of melanomas and the majority of these mutations affect the V600 amino acid residue, leading to a constitutively active BRAF kinase." (PMID 25897843, 2015). "Decreased (<30 %) and increased (>60 %) levels of V600E mutations were detected in 14.8 % and 19 % of mutated BRAF p.V600E melanomas, respectively." (PMID 26141748, 2015). "In our study, p.V600E (c.1799 T > A) was the most common BRAF mutation, occurring in 27 of 34 (79 %) CRCs, 44 of 68 (65 %) melanomas and 7 of 33 (21 %) NSCLCs." (PMID 26498038, 2015).
melanoma (continued). "Approximately 50 % of all melanomas contain a kinase-activating BRAF mutation at codon 600 of exon 15, a majority of which with a substitution of valine with glutamic acid (V600E)." (PMID 25962795, 2015). "Here, we show that when the human melanoma cell line A375SM (containing the active BRAF mutation) is treated with the BRAFi dabrafenib, P-ERK1/2 is significantly reduced, as expected, but Nodal expression is relatively unaffected." (PMID 26460952, 2015). "A critical issue moving forward is to address the molecular mechanisms underlying the resistance of mutant BRAF-expressing melanoma cells to B-RAF inhibition." (PMID 26462148, 2015). "Of the 779 cases, 349 cases were also independently screened by Sanger sequencing and Cobas 4800 BRAF V600 Mutation Test, including 181 CRCs, 127 PTCs and 41 malignant melanomas." (PMID 25784606, 2015). "BRAF mutation is detected in about 40 to 70% of the cases while NRAS mutation is present in 10 to 30% of melanomas." (PMID 25646931, 2015). "A critical issue in the management of BRAF mutated melanoma is the development of resistance to BRAF inhibitors." (PMID 26208478, 2015). "Combination treatment (fisetin + sorafenib) more effectively reduced the growth of BRAF-mutated human melanoma cells at lower doses when compared to individual agents." (PMID 26299806, 2015). "The treatment of melanoma by targeted inhibition of the mutated kinase BRAF with small molecules only temporarily suppresses metastatic disease." (PMID 26029660, 2015). "Although oncogenic mutations are expected to occur in only one of the two parental alleles, we found that only two thirds of BRAF mutated melanomas were heterozygous." (PMID 26141748, 2015). "Following BRAF inhibition, RHOB activates AKT whose inhibition causes hypersensitivity of BRAF-mutant melanoma cells to BRAF inhibitors." (PMID 26098773, 2015). "BRAF mutation analysis of melanoma cells isolated from culture or spiked control blood, or from pilot patient samples was found to match the known BRAF mutation status of the cell lines and primary tumors." (PMID 25807549, 2015). "These include BRAF mutation analysis for melanoma, EGFR and ALK testing for lung cancer and RAS testing for colorectal cancer." (PMID 26101870, 2015). "The recurrent BRAF driver mutation V600E (BRAFV600E) is currently one of the most clinically relevant mutations in melanoma." (PMID 25890285, 2015). "In this study, we screen the BRAF V600E mutation in 779 patients, including 611 CRCs, 127 PTCs and 41 malignant melanoma." (PMID 25784606, 2015). "Vemurafenib and dabrafenib have both demonstrated impressive clinical efficacy with response rates in the region of 50 % in V600 BRAF mutated advanced melanoma." (PMID 26420268, 2015). "In a study of 295 melanoma samples comparing the cobas 4800 BRAF V600 Mutation Test with direct Sanger sequencing assays, the cobas test was less sensitive for mutations other than the single-nucleotide V600E mutation." (PMID 25789737, 2015). "Most common mutation in BRAF is a single substitution of valine to glutamic acid at codon 600 (V600E), accounting for almost 90% BRAF mutations in melanoma." (PMID 26497853, 2015). "We found that combination treatment effectively inhibited BRAF-mutated melanoma cell growth, induced apoptosis, down-regulated MAPK and PI3K signaling pathways in vitro and in vivo." (PMID 26299806, 2015). "At high concentrations, fisetin induced apoptosis in BRAF-mutated melanoma cells as evidenced by cleavage of caspase-3 and PARP, and modulation in Bcl2 family proteins." (PMID 26299806, 2015). "When fisetin was combined with sorafenib, fisetin further augmented the apoptosis-inducing potential of sorafenib in BRAF-mutated melanoma cells." (PMID 26299806, 2015). "To prove the clinical applicability of our method, we tested the plasma of a small cohort of BRAF V600E positive melanoma patients and found the respective mutation in all patients with metastatic cancer." (PMID 26562020, 2015).
melanoma (continued). "MEK inhibitors have already been shown to be effective in BRAF-mutated melanoma patients who had developed resistance to anti-BRAF treatment." (PMID 26456302, 2015). "YAP overexpression was observed in tumors harboring a BRAF mutation from patients with melanoma or NSCLC, and YAP expression levels inversely correlated to the patients’ initial response to RAF and MEK inhibition." (PMID 26389076, 2015). "BRAF is the most commonly mutated oncogene in malignant melanoma, and the BRAF mutation is seen in approximately 50 % of cutaneous melanomas." (PMID 26334521, 2015). "In a phase III trial (CheckMate 037), 405 patients with advanced melanoma who had progressed after receiving ipilimumab, or ipilimumab and a BRAF inhibitor if they were BRAF V600 mutation-positive, were treated with nivolumab monotherapy or chemotherapy." (PMID 26410424, 2015). "In the clinical perspective, BRAF oncogenic activation confers a worse prognosis to human colorectal and thyroid carcinomas and melanomas and is linked to unresponsiveness to traditional and molecular targeted anticancer agents and radioiodine." (PMID 26084290, 2015). "Over activity of the RAS/RAF/MEK/ERK mitogen-activated protein kinase (MAPK) pathway is the hallmark of the majority of melanomas, which is frequently due to mutations in BRAF or NRAS in approximately 50% and 20% of cases, respectively." (PMID 25645078, 2015). "Particularly, BRAF mutations have been identified in about 65% in cutaneous melanomas, representing the most common somatic mutation in melanomas, while on the contrary, there is a striking paucity (3–5%) of BRAF mutations in mucosal melanomas in general." (PMID 25695059, 2015). "Resultant mitogen-activated protein kinase (MAPK) pathway signaling makes some melanomas susceptible to BRAF (BRAF V600 mutations), MEK1/2 (BRAF V600, L597, fusions; NRAS mutations), or other kinase inhibitors (KIT), respectively." (PMID 26084293, 2015). "It is also interesting to note that NRAS mutations are the second most common mutations to occur in melanomas (20%) next to BRAF mutations (50%)." (PMID 26294993, 2015). "In melanomas with BRAFV600 mutation, the MAPK pathway, and therefore the growth of melanoma cells, can be efficiently blocked by BRAF inhibitors such as vemurafenib or dabrafenib." (PMID 25645078, 2015). "In August 2011, vemurafenib was approved by the FDA for the treatment of metastatic or unresectable melanoma with BRAF V600E mutation." (PMID 26705496, 2015). "We also review the current knowledge of the mechanisms underlying resistance to BRAF inhibition and the potential role of melanoma phenotype switching in this process." (PMID 25763355, 2015). "To date, BRAF mutations have been identified in many types of tumors, and are highly frequent in melanoma, colorectal cancer, and papillary thyroid cancer." (PMID 26370727, 2015). "The primary objective of this study was to assess the percentage of BRAF mutated allele (BRAF-M%) in a large series of human melanoma samples." (PMID 26141748, 2015). "Exposure to ultraviolet (UV) radiation induces C > T nucleotide changes at dipyrimidine sites which are responsible for high mutation rates observed in melanomas, particularly those wild-type for both BRAF and NRAS." (PMID 25544760, 2015). "Since the discovery of BRAF mutations in melanoma and other cancers in 2002, a number of studies further identified and characterized BRAF mutations in human cancer." (PMID 29061943, 2015). "Mutations in BRAF have been documented in several human malignancies, including thyroid, ovarian cancer and melanoma where they appear to play an important role." (PMID 26160848, 2015). "BRAF proto-oncogene encodes a serine/threonine kinase regulator of the MAP kinase pathway, and activating BRAF mutations are found in 40–60 % of melanoma, with 90 % of them containing the V600E mutation." (PMID 26697165, 2015).